CDK2 (cyclin dependent kinase 2)
Diseases named in the same sentence as CDK2 in open-access papers (continued):
Sharing a sentence is not in itself a finding about the gene and the disease.
cancer (continued). "Later studies on numerous human cancers, susceptible to CDK2 inhibition, provided cause for more optimism in targeting CDK2 as a potentially valuable target." (PMID 33805800, 2021). "Although CDK2 mutations are rarely observed in human cancers, the CDK2/cyclin E and CDK2/cyclin A pathways are often altered." (PMID 34771669, 2021). "Hyperactivation of Cyclin E/CDK2 causes genomic instability in different experimental models and correlates with an increased frequency of genomic alterations in human cancers." (PMID 34901021, 2021). "In conclusion, this study identified STAT3/CDK2/4/6 as an oncogenic prognosticator of cancer-associated fibroblasts and tumor immune infiltrations, and poor prognosis of multiple cancer cohorts." (PMID 33668805, 2021). "Deregulation in its function or expression are associated to many human cancers, so much that CDK2 inhibition represents a very promising anti-tumor strategy." (PMID 34262648, 2021). "CDK2 is associated mainly with the regulatory subunits including either cyclin A or E with overexpression in human cancer as in ovarian, breast, endometrial, lung and thyroid carcinomas, osteosarcoma, and melanoma." (PMID 34206976, 2021). "Previous studies investigating the process of cell cycle regulation in cancer cells have shown that loss of cyclin B1 function in cells directly results in downregulation of cyclin A and CDK2, leading to cell cycle arrest and induction of apoptosis." (PMID 34685613, 2021). "We show that ADAR1 plays a cancer-promoting role independently of its deaminase activity by binding CDK2 mRNA, underlining the importance of ADARs as essential RNA-binding proteins for cell homeostasis as well as cancer progression." (PMID 33509238, 2021). "In this study, we identified STAT3/CDK2/4/6 as an oncogenic prognosticator of cancer-associated fibroblasts and tumor immune infiltrations." (PMID 33668805, 2021). "Our results revealed that the expression of STAT3/CDK2/4/6 was altered in various cancers and is associated with poor overall and disease-free survival of the cohorts." (PMID 33668805, 2021). "These factors, produced by amniotic stem cells, can regulate the expression of cancer cell proteins associated with the cell cycle, such as cyclin-dependent kinases (CDK2, CDK4, CDK6) and cyclins (cyclin D2, cyclin E1, cyclin H)." (PMID 32972410, 2020). "This contrasts with dependency of cancer cell lines revealed following the genetic loss of CDK2 and particularly CDK9." (PMID 32645016, 2020). "While (R)-roscovitine also inhibits CDK1/5/7/9, specific inhibition of CDK2 by this compound was directly linked to cancer cell apoptosis." (PMID 32543655, 2020). "Cyclin E, in conjunction with its catalytic partner CDK2, has crucial roles in cell division, and cyclin E-CDK2 deregulation causes genome instability and contributes to cancer development and progression." (PMID 30940846, 2019). "The overexpression of CDK2 causes abnormal regulation of the cell cycle, which is directly associated with hyperproliferation of cancer cells." (PMID 31847444, 2019). "This perhaps reflects the generally elevated proliferative capacity of these cancers downstream of core dysregulation by either RB loss or CDK2 activity gain at the G1/S transition." (PMID 30720718, 2019). "Aberrant expression of CDK2 would cause abnormal regulation of cell-cycle, which is directly associated with hyperproliferation of cancer cells." (PMID 29088865, 2017). "Aberrant expression of CDK2 has been associated with hyperproliferation, apoptosis, invasion and migration of cancer cells." (PMID 29088865, 2017).
cancer (continued). "In particular, CDK2 is a key factor regulating the cell cycle G1 to S transition and a hallmark for cancers." (PMID 26147897, 2015). "In support of this scenario, a recent study identified reduced cell-cycle duration as the only common feature of multiple distinct cancers, showing that tumorigenesis could be blocked by mutations affecting CDK2 activity." (PMID 41491041, 2026). "In non-cancer mouse cells, circFoxo3 binds to the cell cycle-associated proteins CDK2 (cyclin dependent kinase 2) and p21 (CDKN1A, cyclin dependent kinase inhibitor 1A), reducing the formation of cyclin E/CDK2 complexes, thereby blocking the G1 to S phase transition in the cell cycle." (PMID 39966624, 2025). "Inhibition of CDK2 and its associated cyclins has displayed promising findings in preclinical investigations and clinical trials, establishing them as a novel category of therapeutic drugs for cancer treatment." (PMID 39770509, 2024). "Activation of p16 leads to the inhibition of the cyclin-dependent kinases CDK4/6 and CDK2, which play a vital role in cell cycle regulation and are implicated in various physiological processes like cancer, tissue regeneration, aging, cellular senescence, and development." (PMID 38686050, 2024). "Unchecked CDK2 activity can lead to uncontrolled cell division, a hallmark of cancer." (PMID 38532893, 2024). "Furthermore, apoptosis and cell cycle regulation depend on the precise modulation of specific cyclins associated with CDKs; cyclins D, E, and CDK2 enhance cancer cell proliferation by modulating the G0/G1 to the S phase transitions in tumor cells." (PMID 38474318, 2024). "Additionally, they demonstrate how the tripartite motif 21 in HHT causes autophagic degradation of the CDK2 protein in cancer cells." (PMID 39496012, 2024). "CDK2 inhibition caused diverse abnormalities within mitotic aneuploid cancer cells." (PMID 38031910, 2023). "Moreover, the abnormal activation of CDK2 leads to uncontrolled cell proliferation during oncogenesis, and is critically associated with tumor growth in various human cancers." (PMID 37626747, 2023). "Cell cycle-related kinase (CCRK) is most closely related to cyclin-dependent protein kinase, which may activate cyclin-dependent kinase 2 and is associated with the growth of human cancer cells." (PMID 36276294, 2022). "Likewise, oncogenic processes of several cancers also have been associated with high levels of the two regulatory subunits of CDK2, cyclins A and E10,11." (PMID 35595767, 2022). "As both low levels of BRCA1 and BRCA1 methylation are very common to BLBC38, and our data demonstrate elevated cyclin E1 in the BRCA1 methylated BLBC, a rational ongoing area of investigation is CDK2 inhibition to sensitize BRCA1 methylated or deficient cancers to PARP inhibitors." (PMID 34465787, 2021). "In this review, we focus on the main functions of Cyclin E/CDK2 complex in normal DNA replication and the molecular mechanisms by which oncogenic activation of Cyclin E/CDK2 causes replication stress and genomic instability in human cancer." (PMID 34901021, 2021). "In this review, we focus on the role of Cyclin E/CDK2 complex in DNA replication and the molecular mechanisms by which hyperactivation of Cyclin E/CDK2 complex causes DNA replication stress and genomic instability in human cancer." (PMID 34901021, 2021). "Furthermore, it is worth noting that genetic alterations in CDK2/4/6 are associated with a poorer prognosis of the cancer cohorts." (PMID 33668805, 2021). "CDK2 expression is highly associated with immune responses in the cancer." (PMID 34409029, 2021).
cancer (continued). "In this study, we use in silico methods to analyze differential expression, prognostic value, genetic and epigenetic alterations, association with tumor-infiltrating immune cells, and cancer-associated fibroblast (CAF) infiltrations of STAT3/CDK2/4/6 in multiple cancer types." (PMID 33668805, 2021). "However, it is unclear what effect prolonged CDK2 inhibition would have on a healthy adult, as CDK2 aids in repairing DNA double-strand breaks, known causes of numerous cancers." (PMID 32543655, 2020). "Hence, there is a need to develop safe and selective inhibitors of CDK2 for the therapeutic management of cancer and associated disorders." (PMID 31847444, 2019). "The abnormal activity of CDK2 is associated with cancer progression and metastasis." (PMID 31847444, 2019). "De-regulation of CDK2 activity has been linked to functional impacts in a variety of cancers." (PMID 29253178, 2018). "Deregulation of CDK2 activity is associated with diseases such as cancer." (PMID 28056778, 2017). "Antiprogestin MF inhibits the growth of different cancer cell lines with a cytostatic effect at lower concentrations in association with a decline in the activity of the cell cycle regulatory protein Cdk2, and apoptotic lethality at higher doses in association with increased hypodiploid DNA content." (PMID 21619605, 2011). "Cyclin D and cdk2 are two important regulatory molecules that are associated with the G1-S phase transition of cell cycle and expression of these two molecules are significantly correlated with the degree of malignancy in a variety of human carcinomas." (PMID 21625458, 2011). "Loss of CDK2 presents a different challenge to cell lines, aside from the more conventional role to regulate cyclins, which in turn might lead to altered DNA damage response and checkpoint activation, mutations in DNA repair genes drive cancer development." (PMID 33909629, 2021). "Also, STAT3 is closely associated with VEGF or CDK2 in cancer progression." (PMID 29254203, 2017). "Previous studies have shown that elevated CDK2 and CDK6 expression is associated with chemoresistance and poor survival in various cancers." (PMID 41487280, 2026). "Experimentally, GR treatment markedly reduced both mRNA and protein expression levels of CDK2 in HeLa cells, establishing CDK2 as a central mediator of GR’s anti-cancer activity." (PMID 41614894, 2026). "Cancer progression is driven by dysregulation of cyclin-dependent kinase 2 (CDK2), a critical cell cycle regulator." (PMID 41888226, 2026). "CDK2 is a multifunctional kinase involved in many critical cellular processes, including cell cycle progression, differentiation, cancer, immunity, etc.." (PMID 41532831, 2026). "We subcutaneously implanted WT and Cdk2-/- cancer cells into C57 mice and Tlr4-/- mice respectively." (PMID 40557162, 2025). "We found that mice bearing Cdk2-/- cancer cells exhibit slower tumor growth than WT cells after anthracycline analogue MTX treatment, and this phenomenon is dependent on the immune system." (PMID 40557162, 2025). "The findings presented here provide a rationale for pursuit of combination CDK2-based cancer therapy." (PMID 40232858, 2025). "Despite its promising in vitro efficacy, PF-06873600’s clinical development was discontinued due to significant toxicity, underscoring the challenges in simultaneously targeting multiple Cyclin-dependent kinases (CDK2/4/6) to treat human cancers." (PMID 40282469, 2025).
cancer (continued). "The contributions of aberrant cyclin E/CDK2 signaling in resistance to therapies reveal an important element that needs to be clearly understood concerning cancer progression." (PMID 40227591, 2025). "For example, curcumin induces cell cycle arrest in the G1 phase by targeting cyclin-dependent kinase 2 (CDK2) activity, thereby suppressing cancer cell proliferation." (PMID 41301813, 2025). "Although CDK-1 can substitute for CDK-2 in normal cells, CDK-2 becomes essential in malignant cells, facilitating cancer growth." (PMID 40901864, 2025). "The approval of CDK4/6 inhibitors has spurred interest in next-generation of CDK2 inhibitors, which show potential in cancer therapy." (PMID 39800748, 2025). "Molecular docking studies revealed that the newly designed compounds exhibited better binding affinities, ranging from −7.2 to −9.8 kcal/mol, to key cancer-related targets (CDK2, EGFR, and Tubulin)." (PMID 40526618, 2025). "Both metrics were analyzed, but AUC remains the gold standard for direct comparison with prior radiomics studies, such as those investigating RAD51, SCN3B, and CDK2 in cancer biomarker discovery." (PMID 40535132, 2025). "More specifically, ASPM-2 can influence the biological behavior of cancer cells by increasing their cell cycle stability and interacting with the Cdk2/cell cycle protein E (Cyclin E) complex." (PMID 40979592, 2025). "Isatin derivatives represent a promising class of CDK2 inhibitors with potential applications in cancer therapy." (PMID 40076766, 2025). "CYC065 treatment was selected for analyses because this agent is undergoing clinical trial testing, and its antineoplastic effects are conferred through CDK2/9 inhibition, although the death of multipolar cancer cells was largely conferred by CDK2 antagonism." (PMID 40232858, 2025). "Cyclin-dependent kinase 2 (CDK2) equally plays a crucial role in cancers, especially that of cell cycle regulation." (PMID 40649898, 2025). "In many cancers, including breast cancer, CDK2 becomes dysregulated, allowing uncontrolled cell proliferation." (PMID 39861131, 2025). "We propose that pharmacologic elimination of persistent polypoid cancer cells within lung tumors will enhance clinical efficacy of CDK2 inhibitors." (PMID 40232858, 2025). "In tumors driven by MYC overexpression, CDK2 activity is vital for preventing senescence and enabling cancer cell immortalization." (PMID 39800748, 2025). "Together, our above studies indicate that the increase of MTX-induced immunogenicity in tumors carrying Cdk2-/- cancer cells were dependent upon the elevated type-1 interferon response." (PMID 40557162, 2025). "By subcutaneously implanting restoration of Cdk2-/- cancer cells with WT Cdk2 or Cdk2T160A into C57 mice, we observed that the combination of Cdk2T160A cells with MTX remained more effective than the replenished Cdk2-/- cancer cells." (PMID 40557162, 2025). "Activation of the cyclin E/CDK2 complex promotes uncontrolled cell proliferation and malignant transformation, highlighting the cyclin E/CDK2 complex as a promising target for therapeutic intervention in cancer treatment." (PMID 40227591, 2025). "Here, the authors investigate CDK2-dependancy and response to CDK2 inhibition across different cancers, identifying markers of sensitivity and combinatorial therapeutic strategies." (PMID 39924553, 2025). "Several studies have demonstrated that inhibition of CDK2 can induce cell cycle arrest and apoptosis in cancer cells while sparing normal cells, which aligns with the aim of our study to identify potential anticancer agents." (PMID 41286335, 2025).
cancer (continued). "It was reported that prolonged CDK2 inhibition increased cancer cell reliance on the CDK1 pathway, while rapid adaptation depended on expression of the CDK4/6 pathway." (PMID 40232858, 2025). "Accumulating evidence indicates that CDK-2 promotes hyperproliferation of cells and induces the progression of cancer cells." (PMID 41009865, 2025). "Targeting CDK2 and its cyclin partners has emerged as a promising strategy in cancer therapy, and several CDK2 inhibitors have progressed to clinical trials." (PMID 41007649, 2025). "Among the most critical molecular targets in cancer therapy are Cyclin-Dependent Kinase 2 (CDK2), Epidermal Growth Factor Receptor (EGFR), and Tubulin, each of which plays a pivotal role in tumor progression and development of drug resistance." (PMID 40526618, 2025). "The development of dual inhibitors such as 2‐mercaptobenzoxazole derivatives, which target EGFR, HER2, VEGFR2, and CDK2, exemplifies the growing trend toward multitargeted cancer therapies designed to overcome a range of resistance mechanisms." (PMID 41523619, 2025). "The abnormal CDK2 activation results in uncontrolled cell growth and cell division in various human cancers." (PMID 39820173, 2025). "This study built on this prior work by elucidating the proportion of cancer cells that elicit anaphase catastrophe relative to mitotic catastrophe during multipolar mitosis after CDK2 inhibition." (PMID 40232858, 2025). "Treatment with the CDK2/9 inhibitor CYC065 (Fadraciclib) having antagonism of CDK2 > CDK9 substantially increased the presence of cancer cells with multipolar mitotic spindles across diverse aneuploid cancer cells." (PMID 40232858, 2025). "This indicated that the persistence of these multinucleated and multipolar cells revealed the presence of a residual population of aneuploid cancer cells despite continuous CDK2 inhibition." (PMID 40232858, 2025). "Combined targeting of CDK2 with CDK1 or kinesin family member antagonists should eliminate polyploid cancer cells, promote apoptosis, and augment antineoplastic effects." (PMID 40232858, 2025). "As a core regulator of cell cycle, CDK2 becomes activated during the late G1 phase and remains active throughout the S phase, playing a critical role in cancer cell proliferation." (PMID 40740234, 2025). "In cancer treatments, CDK2 inhibitors can specifically target CDK2 in cancers where it is a primary driver, minimizing the toxicity and dose limitations associated with inhibiting CDK4 and CDK6." (PMID 40149983, 2025). "Certain isatin derivatives exhibit potent inhibitory activity against CDK2 and related kinases, inducing cell cycle arrest and apoptosis in various cancer cell lines." (PMID 40076766, 2025). "Another finding from this study is the emergence of multinucleated cancer cells that appeared after CDK2 inhibitor treatments." (PMID 40232858, 2025). "Because the recent advancements in CDK2 research are inadequate, the link between CDK2 activity and cancer development remains uncertain." (PMID 40486867, 2025). "One way to eliminate this persistent cancer cell population is to explore combination therapy with CDK2 inhibitors in concert with another centrosome targeting agent." (PMID 40232858, 2025). "The objective behind the synthesis these analogues were to develop active CDK2 suppressors with enhanced efficacy against cancer cells characterized by overexpression of CDK2." (PMID 38398626, 2024). "A series of derivatives, based on dichlorophenoxymethyl and featuring various nitrogenous heterocyclic rings were synthesized and evaluated on cancer cell lines and the CDK2 enzyme." (PMID 39404419, 2024). "The transition from G1 to S phase is driven by CDK2 in complex with its canonical partner cyclin E1 (CCNE1), which is often amplified in various cancers and is associated with worse survival outcomes in patients with breast, ovarian, and other malignancies." (PMID 38531837, 2024).